IL10 (interleukin 10)
Diseases named in the same sentence as IL10 in open-access papers (continued):
Sharing a sentence is not in itself a finding about the gene and the disease.
Stroke (continued). "Interleukin (IL)-1beta, TNF-alpha, and IL-4 mRNA levels were higher, while IL-10 mRNA levels were reduced in total monocytes from patients versus controls, at either 24 h or 48 h after stroke." (PMID 34201498, 2021). "To further investigate the temporal dynamics and the cellular source of IL-10, we measured mRNA levels of Il10 transcripts in CD45intermediate, CD11bhigh microglia and CD45high, CD11bhigh, Ly6gnegative macrophages on days 3, 7, and 14 post-stroke." (PMID 34772416, 2021). "Of note, the AUCs for GDF-15, D-dimer, ADAMTS13, CCL2/MCP-1, IL-4, CC4b, IL-7, ferritin, SAA, CCL1/I-309 and IL-10 were ≥0.75 in indicating stroke amongst children with TBM." (PMID 33930055, 2021). "Disrupted microbiota composition accompanied by an elevated level of proinflammatory IL-17 and a decreased level of neuroprotective IL-10 were observed in stroke mice, and an elevated TMAO level was reported in patients with acute ischemic stroke." (PMID 35153980, 2021). "IL-10 overexpressing animals showed reduced short-term infarct volumes and apoptosis after pMCAO, while exogenous administration of IL-10 demonstrated therapeutic potentials by limiting post-stroke inflammation." (PMID 33770265, 2021). "IL1B, IL10, TNF, IL6, and ICAM1 are closely related to the inflammatory response after stroke, among which IL-10 is an important anti-inflammatory factor, while L1B, TNF, and IL6 are proinflammatory factors." (PMID 33727944, 2021). "Polyclonal stimulation with PMA-Ionomycin also showed higher percentages of CD3+ lymphocytes producing IFN-γ, TNF-α, or IL-10 at admission compared to day 5 after stroke." (PMID 32719588, 2020). "Several studies have shown that immune responses including IL6, IgA, CXCL16, TNFSF4, and IL10 were involved in stroke." (PMID 31899762, 2020). "The same was observed in terms of the level of PD-L1 expression, which was higher on IL-10+ than on IL-10− monocytes on day 1 after stroke (p = 0.0063)." (PMID 33329318, 2020). "Whereas IL-10 producing lymphocytes were upregulated at admission, the proportion of T lymphocytes producing IL-4 increased all over the 90 days from the onset of stroke." (PMID 32719588, 2020). "In conclusion, the decreased release of some pro-inflammatory cytokines (IP-10, TNFα, IL-1β, and IL-12p70) and increased release of IL-10 and IL-8 after ex vivo blood stimulation with LPS are related to poor outcome after stroke." (PMID 31906994, 2020). "The decrease mRNA levels of Arg-1 and IL-10 were markedly showed in stroke and stroke+PBS groups and less than that of the sham group (∗∗P < 0.01, ∗∗∗P < 0.001)." (PMID 32908485, 2020). "Despite these limitations, we were able to identify increased production of both proinflammatory TNF-α, and anti-inflammatory IL-10 in response to neural peptides in lymphocytes of stroke patients at admission vs. day 5 post-stroke." (PMID 32719588, 2020). "In the context of experimental cerebral ischemia, several studies have demonstrated that IL-10 is a key neuroprotective cytokine involved in the regulation of post-stroke neuroinflammation." (PMID 32111174, 2020). "As shown on an animal model of brain damage, IL‐6 and IL‐10 release results from sympathetic activation as well as catecholamine release due to increased intracranial pressure following the occurrence of stroke." (PMID 32583980, 2020). "Our new data show that this reduction is restricted to IL-10− monocytes, while IL-10-expressing monocytes remain fully HLA-DR competent after stroke." (PMID 33329318, 2020). "Using quantitative reverse transcription-PCR, we confirmed increased mRNA expression of LCN2 as well as anti-inflammatory cytokines-Arg1, IL-10, and decreased mRNA level of pro-inflammatory cytokines-IL-6, IL-23 in the tumor of cancer-bearing stroke mice." (PMID 32153594, 2020). "It has been demonstrated that treatment with IL-10-producing B-cells has been shown to reduce infarct size and peripheral and brain inflammation in an experimental stroke model." (PMID 32714088, 2020).
Stroke (continued). "Lower levels of IL-10 were shown in plasma within 12 hours of stroke, and IL-10 levels are increased 24 hours after tissue-type plasminogen activator treatment." (PMID 32244523, 2020). "IL-10-positive monocytes are more activated post-stroke, as indicated by their increased HLA-DR expression." (PMID 33329318, 2020). "Cytokine-based multimarker score composed of ex vivo released IL-12, IL-10, TNFα, and plasma IL-6 adds prognostic value to clinical model for predicting stroke outcome." (PMID 31906994, 2020). "The decreased ex vivo release of pro-inflammatory cytokines and increased release of IL-10 and IL-8 are related to poor outcome after stroke." (PMID 31906994, 2020). "In another pathway, SP1 → IL10 → stroke, SP1 positively regulates the transcription of IL10, which has been successfully used as a therapeutic mediator to reduce post-stroke secondary neuroin-flammation." (PMID 33092540, 2020). "IL-10 producing T lymphocytes also increased after stroke onset, suggesting that stroke generated a new homeostatic level to offset the previous inflammatory context, and this counterbalance is set within the T cell compartment." (PMID 32719588, 2020). "A previous study comparing IL-10 serum levels between stroke patients and healthy population reported contrary results, finding lower levels of IL-10 in stroke patients compared to controls." (PMID 32111174, 2020). "Previous work has shown that IL-10 can reduce inflammation after spinal cord injury, stroke, and TBI." (PMID 30611291, 2019). "The knockdown of miR-181a enhanced the production of pro-inflammatory cytokines (TNF-α, IL-6, IL-1β, IL-8), and increased levels of the anti-inflammatory cytokine IL-10 result from miR-181 over-expression in a murine stroke model." (PMID 30953275, 2019). "Regulatory T cells and B cells attenuate inflammation after stroke by producing anti-inflammatory cytokines such as IL-10, transforming growth factor-β (TGF-β)." (PMID 31572378, 2019). "In the sub-acute phase of neuroinflammation at 3 days post-stroke, TNFα and IL-10 mRNA expression was substantially elevated in vehicle-treated stroke mice compared to sham mice." (PMID 31138227, 2019). "At 4 h post-stroke with clenbuterol treatment, we observed a significant decrease in TNFα gene expression in the stroke condition accompanied by a trend towards an increase in IL-10 gene expression." (PMID 31138227, 2019). "The infarct volume, as well as serum levels of matrix metalloproteinase-9 (MMP-9) and interleukin-10 (IL-10), were measured one week after stroke." (PMID 31807255, 2019). "We observed a trend towards an increase in the anti-inflammatory cytokine IL-10 with clenbuterol treatment in stroke mice (p = 0.077)." (PMID 31138227, 2019). "On the other hand, increasing the level of IL-10 is related to the reduction of injury after middle cerebral artery (MCA) occlusion, which suggests the neuroprotective role of IL-10 in stroke." (PMID 31807255, 2019). "The earlier acute pro‐inflammatory response appears specific to the colon as circulating serum levels of TNF‐α and IL‐10 remain unchanged at both the 5‐ and 24‐hr time point following stroke." (PMID 31199577, 2019). "VAC extract and estrogen groups significantly increased the levels of IL-10 compared with the control group one week after the stroke (all P<0.05)." (PMID 31807255, 2019). "There was a positive correlation between the concentration of IL-10 and the residence time of Accelerated Rotarod test at day 21 after stroke (r = 0.668, P = 0.013)." (PMID 31810470, 2019). "B lymphocytes in the acute phase of stroke are protective against damage of nervous tissue by release of IL-10, which inhibits the production of pro-inflammatory cytokines by T lymphocytes." (PMID 31514749, 2019). "Knockdown of H19 by siRNA in MCAO rats reduced brain infarct as well as TNF-α and interleukin-1β (IL-1β), and it increased plasma interleukin-10 (IL-10) concentrations 24 h after stroke." (PMID 29651234, 2018).
Stroke (continued). "Stroke-induced monocyte dysfunction resulted in an increase of the interleukin-10 (IL-10) level as well as a decrease of the interleukin-6 (IL-6), tumor necrosis factor-α (TNF-α) and interleukin-1β (IL-1β) levels." (PMID 29636059, 2018). "M2 microglia are beneficial for resolving post-stroke inflammation by secreting anti-inflammatory cytokines such as IL-10 and TGF-β in addition to neurotrophic factors." (PMID 29895321, 2018). "In contrast, the levels of anti‐inflammatory cytokines (IL‐4 and IL‐10) increased and peaked at 10 days of stroke." (PMID 29131464, 2018). "Transcript levels of Tnfa were also reduced in the spleens of mice 1–5 days after experimental stroke in comparison to sham-operated controls whereas Il-10 transcript was marginally increased above baseline." (PMID 29872438, 2018). "On the other hand, IL-10 is an anti-inflammatory cytokine that inhibits the inflammatory response, playing protective effects after stroke." (PMID 30245755, 2018). "IL-10 levels in patients with acute cerebral infarction can increase at the initial stage of stroke, and IL-10 levels are positively correlated with disease severity, which is in line with the results of the present study." (PMID 30245755, 2018). "In a permanent middle cerebral artery occlusion (MCAO) model, IL-10−/− C57BL/6 mice have 30% larger infarct volumes compared with WT mice 24 h post-stroke." (PMID 28659854, 2017). "Similar results were seen in a Russian population, where the IL-10 627*C/*C genotype is protective against hypertension in male patients with stroke." (PMID 28659854, 2017). "The results from this pilot study clearly point to a strong correlation between stroke severity, peripheral iNKT cell activation, IL-10 production, and severe immunosuppression." (PMID 28154551, 2017). "While localized IL-10 production in the brain is neuroprotective after stroke, we and others have found that peripheral levels of IL-10 are closely correlated with worsening of stroke outcome." (PMID 28154551, 2017). "In our study, the serum levels of TNF-α, CRP, IL-4, and IL-10 were all significantly increased in stroke patients, whereas, the serum level of IFN-γ was decreased compared with that in control subjects." (PMID 27682880, 2017). "Regulatory B cells contribute to limiting the inflammatory events occurring in CNS following stroke and IL-10 secreting B cells appear to have the major role in this mechanism." (PMID 28373915, 2017). "Overexpression or administration of IL-10 has been reported to reduce brain injury and improve neurological outcomes in experimental stroke." (PMID 28936196, 2017). "We cannot confirm the increased peripheral IL-10 level after stroke was attributed by iNKT cell activation as that would require flow cytometric analysis of intracellular cytokine production of live iNKT cells." (PMID 28154551, 2017). "We observed that low stroke risk patients exhibited higher GATA-3, Foxp3, PU.1, AHR, IL-9, IL-10 and IL-22 expression levels than did patients with high stroke risk." (PMID 27115869, 2016). "The ratio between the pro-inflammatory TNF- to the anti-inflammatory IL-10 is reduced during the period of the stroke related infection." (PMID 27430328, 2016). "In particular, IL-10 secretion by monocytes, dendritic cells, and Tregs is greatly increased after stroke in both mice and humans, and can act upon many immune cell types to avert from a pro-inflammatory response." (PMID 26742037, 2016). "Nevertheless, our findings strongly suggest that inhibition of sympathetic actions is an effective approach for reversing HLA-DR decrease and IL-10 increase in stroke patients, paving the way towards more effective therapies for SAI." (PMID 27409177, 2016). "Experimental and clinical studies show that monocytes, dendritic cells, and Tregs greatly increase secretion of IL-10 after stroke, averting a pro-inflammatory response." (PMID 27923376, 2016).
Stroke (continued). "In a mid cerebral artery model of stroke, IL-10 administration was found to suppress overexpression of proinflammatory mediators IFNγ and TNFα and reduce lesion volume." (PMID 27022620, 2016). "In this study, we demonstrated that patients with low stroke risk have increased mRNA expression of GATA-3, Foxp3, PU.1, AHR, IL-9, IL-22 and IL-10." (PMID 27115869, 2016). "Accordingly, in the inhibitor samples, IL-10 increased fivefold at 7 days after stroke, as compared to expression at 48 h." (PMID 27829437, 2016). "Regulatory T and B cells attenuate post-stroke inflammation by producing anti-inflammatory cytokines (e.g., IL-10, TGF-β)." (PMID 27492770, 2016). "Delayed (6–7 days) elevation of IL-10, IL-4, and IL-17 in the post-acute phase of stroke was previously reported by other authors." (PMID 27829437, 2016). "One study showed that IL-10 levels were significantly lower at 6 h in stroke mice compared to sham mice but were increased at 24 and 72 h post-stroke; however, only male animals were examined." (PMID 26462256, 2015). "IL-10 and CRP at 6 h, as well as NIHSS on admission, were identified as independent predictors of stroke-associated infection." (PMID 25613713, 2015). "Larger cohorts are needed to confirm these findings and to investigate the relationship between IL-10, stroke outcomes, and post-stroke infection." (PMID 26462256, 2015). "Others have found that in age-matched adult female and male mice subjected to cardiac ischemia and reperfusion injury that females had increased IL-10 mRNA expression vs. males, similar to that seen in female stroke patients in this study." (PMID 26462256, 2015). "Multiple studies have shown that IL-10 plays an important role in ameliorating the neuroinflammatory response in animal stroke models." (PMID 26166952, 2015). "This suggests that IL-10 is related to other factors that affect stroke outcome, likely stroke severity or age." (PMID 26462256, 2015). "In conclusion, we found significant difference in IL-10 concentration between patients with cardioembolic sources and large-artery atherosclerosis in acute-phase of stroke." (PMID 25923658, 2015). "IL-10 was entered as a continuous predictor following a logarithmic transformation to normalize its distribution; other covariates included age, stroke severity at admission (as measured by NIHSS), heart disease, and high cholesterol." (PMID 26462256, 2015). "In rodent models of stroke, systemically administrated IL-10 reduces the cerebral infarction volume after stroke." (PMID 25923658, 2015). "More specifically IL-1, IL-6, IL-10, IL-17, IL-23, TNFα, transforming growth factor β (TGFβ) and IFNγ are seen to increase after stroke, IL-17, IL-23 and IFNγ being associated with exacerbation of stroke in mice, whereas IL-10 and TGFβ are protective." (PMID 25705177, 2015). "In this study, we investigated the relationship between IL-10 levels and stroke outcomes in males and females." (PMID 26462256, 2015). "In ischemic stroke, an excessive IL-10 response contributes to post-stroke immunosuppression, which worsens outcomes." (PMID 26462256, 2015). "In a mouse stroke model, there is increased sympathetic drive which induces iNKT cells to make more IL-10 and less IFN-γ." (PMID 26042123, 2015). "IGF-1 induced Akt activation was preceded by a reduction of blood brain barrier permeability at 4h post-stroke and global suppression of cytokines including IL-6, IL-10 and TNF-α." (PMID 24618563, 2014). "These authors suggest that B cells secreting IL-10, a known post-stroke neuroprotectant, reduce ischemic injury by modulating subsequent neutrophil diapedesis and pro-inflammatory chemokine production." (PMID 24485041, 2014). "This study investigated the endogenous expression of IL-10 and its receptor in the rat brain after experimental stroke." (PMID 24499655, 2013). "The release of IL-10 from T-regulatory cells has been shown to control the inflammatory response following stroke and can lead to a smaller infarct size." (PMID 23483951, 2013).
Stroke (continued). "The release of IL-10 from T-regs has been shown to decrease inflammation and a subsequent decrease in infarct volume after stroke." (PMID 23483951, 2013). "Patients with lower IL-10 levels also showed greater infarct growth during the first 72 hours following the onset of the stroke." (PMID 23773291, 2013). "Following stroke, the IL-10 transcript expression peaked at 6 h after reperfusion for both ages of mice (2.1-fold, adult p≤0.05, aged p≤0.01)." (PMID 22028848, 2011). "The anti-inflammatory cytokine IL-10 reaches its peak expression between 2-7 days after stroke onset and limits the production of proinflammatory agents through negative feedback mechanisms." (PMID 21450100, 2011). "Nevertheless, we obtained a strong trend towards a stroke-induced increase in the levels of IL-10 in the infarct core (p = 0.06)." (PMID 21714902, 2011). "The anti-inflammatory cytokine IL10 was significantly increased only in the plasma of LPS-preconditioned mice compared to saline preconditioned mice following stroke." (PMID 21999375, 2011). "For instance, IL10 has been shown to be cerebroprotective in the setting of experimental stroke and soluble receptors of TNF-α limit its cardiotoxicity." (PMID 20300185, 2010). "IL-10 is a cytokine that is produced by the Treg cells and seems to play an important role during a stroke." (PMID 19919699, 2009). "A central finding of this work is the model’s ability to reproduce the temporal decoupling between pro- and anti-inflammatory cytokines, with TNF-α and IL-6 rising sharply during the early post-stroke phase, and IL-10 emerging only after a defined temporal threshold." (PMID 41557608, 2026). "Second, although the TNF-α/IL-6/IL-10 triad is central to stroke inflammation, additional mediators such as interferon-γ, MCP-1, and most notably, the critical driver IL-1β, along with cellular actors like microglia subtypes and peripheral leukocytes, are not explicitly modeled." (PMID 41557608, 2026). "Notably, simulations of IL-10 knockout conditions produced infarct volume estimates consistent with rodent stroke experiments, yielding a correlation coefficient of R2=0." (PMID 41557608, 2026). "It has been reported that within 1 year after stroke onset, inflammatory markers such as interleukin-6 (IL-6), interleukin-10 (IL-10), and tumor necrosis factor-alpha (TNF-α) are significantly elevated, with notable increases in the IL-6/IL-10 and TNF-α/IL-10 ratios." (PMID 41458124, 2025). "IL-10 protects OPCs post-stroke by reducing lipid ROS and ferroptosis." (PMID 40880849, 2025). "Within the first 24 h after the stroke, we observed the increased expression of several key factors, including calcium-binding proteins, peroxiredoxins, heat shock proteins and interleukins (1α and 1β, IL10, IL17α)." (PMID 40332314, 2025). "For example, in the treatment of nonalcoholic steatohepatitis, self‐protection is mainly through IL‐10 secretion by M2‐like macrophages, while in stroke, it is mainly through elevated CCR5 expression and chemotactic DNT infiltration into the lesion site to exert inflammatory protection." (PMID 39844773, 2025). "Ultimately, IL-10 serves as both a marker of immune balance and a potential indicator of whether inflammation is being adequately regulated in the aftermath of stroke." (PMID 40869247, 2025). "There was also an increase in the anti-inflammatory cytokine IL-10, which, along with IL-17 due to its production by gamma delta (γδ) T cells, may play an emerging role in the intestinal immune response during stroke." (PMID 40143100, 2025). "Studies have shown that treadmill training can effectively improve stroke-induced Th17/Treg immune imbalance, upregulate the expression of anti-inflammatory factor IL-10 and transcription factor Foxp3, and downregulate the levels of pro-inflammatory factor IL-17 and transcription factor RORα." (PMID 40837062, 2025).